EIF1AXP1 (EIF1AX pseudogene 1)
Synonyms: formerly EIF1AP1
Gene: Transcribed processed pseudogene on chromosome 1 (16,685,621 to 16,686,055, reverse strand). Ensembl gene ENSG00000236698.
Diseases named in the same sentence as EIF1AXP1 in open-access papers:
EIF1AXP1 is named in the same sentence as 2 diseases in open-access papers, as found by Europe PMC text mining. Sharing a sentence is not in itself a finding about the gene and the disease. The quoted sentences say what the papers report.
cancer (1 paper, 2025). A tumor composed of atypical neoplastic, often pleomorphic cells that invade other tissues. "Mann-Whitney U tests in TARGET and TCGA mRNA profiles showed a female bias in all tested cancer types for EIF1AX and 21 cancer types for EIF1AXP1 (p-value < 0.05)." (PMID 39975298, 2025).
EIF1AXP1 also shares sentences with these, for which no sentence is quoted: acute myeloid leukemia (1 paper).